REN (renin)
Diseases named in the same sentence as REN in open-access papers (continued):
Sharing a sentence is not in itself a finding about the gene and the disease.
Hypertension (continued). "However, since 20-HETE is a potent vasoconstrictor, and is involved with the renin-angiotensin system to promote hypertension, vasoconstriction, and vascular dysfunction, we evaluated the effect of inhibiting ω-hydroxylases by DDMS." (PMID 28328948, 2017). "In fact, menopausal women who successfully lost 5% of their body weight decreased their SBP by 7 mmHg and had lower angiotensinogen, renin, aldosterone, and angiotensin converting enzyme levels, providing experimental evidence for this effective means of treating obesity-related hypertension." (PMID 28993801, 2017). "As for the underlying mechanism responsible for these effects, it has been suggested that hyperuricemia reduces nitric oxide production in the vascular endothelium and increases the concentrations of renin and angiotensin, thereby impairing renal blood flow and triggering high blood pressure." (PMID 28203292, 2017). "It was a shame since uric acid contributes significantly to the pathogenesis of high blood pressure by activating the renin–angiotensin–aldosterone system directly at the vascular level and indirectly by inducing tubule-interstitial disease and consequent impaired baroreflex function." (PMID 28049502, 2017). "Renin activates angiotensinogen into angiotensin I, and ACE can split angiotensin I into active angiotensin II, which can cause vasoconstriction and lead to high blood pressure." (PMID 29137154, 2017). "Angiotensin receptor blockers may be an appropriate first-line agent for postmenopausal women with hypertension because the activation of renin–angiotensin–aldosterone system is suggested as one possible mechanism of postmenopausal hypertension." (PMID 27258507, 2016). "In addition, the multitude of contributing factors (environment, sodium intake, renin, insulin resistance, sleep apnea and age, among others) makes hypertension complex to study mainly due to the genetic component associated with its appearance." (PMID 27009470, 2016). "Reactive fibrosis or interstitial fibrosis has mostly been described in hypertension, DM, aging heart and idiopathic dilated cardiomyopathy where the activation of renin-angiotensin aldosterone system, beta-adrenergic system and the excess of reactive oxygen species are major contributors." (PMID 26846306, 2016). "Several soil‐derived Actinobacteria produce secondary metabolites that are proven specific and potent inhibitors of the human angiotensin‐I‐converting enzyme (ACE), a key target for the modulation of hypertension through its role in the renin–angiotensin–aldosterone system." (PMID 27754586, 2016). "This study examined the effect of Carthamus tinctorius (CT) extract plus captopril treatment on blood pressure, vascular function, nitric oxide (NO) bioavailability, oxidative stress and renin-angiotensin system (RAS) in Nω-Nitro-l-arginine methyl ester (l-NAME)-induced hypertension." (PMID 26938552, 2016). "Plasma renin concentration (PRC) is used as a clinical parameter related to hypertension." (PMID 27052373, 2016). "Whether CD renin is important in other forms of Ang-II independent hypertension remains to be determined." (PMID 27467376, 2016). "In obese dogs, hypertension can occur by different mechanisms including the activation of the renin-angiotensin-aldosterone axis, hyperadrenergic activation and insulin resistance causing hyperadrenergic activation, and increased production of angiotensin and proinflammatory cytokines." (PMID 28058131, 2016). "While CD renin appears to play a significant role in Ang-II hypertension, its role in Ang-II independent hypertension is currently unknown." (PMID 27467376, 2016). "A similar phenomenon has been described in another renin-driven transgenic model of hypertension." (PMID 27625610, 2016).
Hypertension (continued). "As the statistically significant plasma sodium increase was found in ISIAH rats as compared to WAG, the low-renin hypertension in ISIAH rats may arise due to the suppression of the RAS by the sodium retention and elevated blood pressure." (PMID 26821914, 2016). "Many studies have reported associations between single nucleotide polymorphisms (SNPs) of renin–angiotensin–aldosterone system (RAAS) genes and CVDs (particularly hypertension), and their findings have provided candidate SNPs for research on genetic correlates of PIH." (PMID 27910864, 2016). "In fact, it is conceivable that, in this condition, ACTH-induced adrenal renin secretion may compensate inhibition of renal renin synthesis by hypervolemia and hypertension secondary to cortisol excess." (PMID 27489549, 2016). "This study explained that the reduction in IL8RA could influence the renin–angiotensin–aldosterone system II, which plays an important role in blood pressure and thereby hypertension." (PMID 27918443, 2016). "TTRhRen mice develop renin-dependent hypertension through constitutive expression of the human pro-renin cDNA, and when these mice are back-crossed to OVE26 mice, they develop significant albuminuria, mesangial expansion, tubulointerstitial fibrosis, and a decline in renal function by 20 weeks." (PMID 26814757, 2016). "Renin–angiotensin system inhibitors (RASIs), including angiotensin-converting enzyme inhibitors (ACEIs), angiotensin II receptor blockers (ARBs), and direct renin inhibitors, are commonly used in hypertension treatment." (PMID 27632175, 2016). "In the circulation, a drop in blood pressure (systemic hypotension) and/or blood volume results in juxtaglomerular cells within the kidneys to release renin (protease) whereas increased blood pressure (hypertension) inhibits renin release under normal circumstances." (PMID 27761230, 2016). "Furthermore, the alterations of renin-angiotensin system and hypertension presented in MS rats were reversed with treatment with asiatic acid." (PMID 27121076, 2016). "Several previous studies showed that the renin-angiotensin system plays a crucial role in the development of hypertension in high fructose fed rats, since an increase in plasma Ang II and AT1 receptor mRNA levels were reported in fructose-induced hypertensive rats." (PMID 27121076, 2016). "In some non-Caucasian ethnic groups, the so-called “low renin-hypertension” is an important, and sometimes overlooked, cause." (PMID 27774451, 2016). "Furthermore, incommensurate activation of the peripheral RAS, had been validated by a significant increase in plasma renin activity, which exists after development of hypertension." (PMID 27225778, 2016). "Collectively, these studies suggest that CD renin may be important in pathological states such as hypertension and diabetes." (PMID 27467376, 2016). "The main objective of the current study was to examine whether CD renin KO attenuates hypertension and renal injury in DOCA-salt hypertension." (PMID 27467376, 2016). "Moreover, PRR is a newly discovered component of the renin-angiotensin system (RAS) which has associated with diabetic nephropathy, hypertension and insulin resistance." (PMID 28874965, 2016). "This proves that elevated renin activity is the cause of the severe colitis, but does not exclude the involvement of high blood pressure because aliskiren also lowers blood pressure." (PMID 27271344, 2016). "We hypothesized that a high salt intake causes an increase in tissue levels of prorenin, renin, (P)RR, angiotensin II and angiotensin II AT1 receptor, and damages the heart at an early stage of hypertension." (PMID 25799069, 2015). "Given the role of impairments in the renin-angiotensin system (RAS) in the pathogenesis of hypertension and metabolic syndrome, recent research has also focussed on the potential beneficial effects of drugs targeting RAS pathway on other aspects of metabolic diseases." (PMID 25714093, 2015).
Hypertension (continued). "Hypertension is a complex cardiovascular disease and contributes to worldwide morbidity and mortality, while its pathogenesis is closely related to abnormalities of the renin-angiotensin aldosterone system (RAAS)." (PMID 25815211, 2015). "Several studies have identified SNPs in genes related to the renin hypertension." (PMID 26495141, 2015). "Similar to patients with low-renin hypertension, Gata5-null mice respond well to thiazide therapy and may be a useful model to further analyse the pathophysiology and progression of disease." (PMID 26617239, 2015). "Among the patients with type 2 diabetes, the mean age, duration of diabetes, use of renin-angiotensin system inhibitors or statins, hypertension, hyper-LDL-cholesterolemia, and hypo-HDL-cholesterolemia were significantly higher in the subjects with CHD than in those without CHD." (PMID 26064988, 2015). "Indeed, treatment is primarily centered on controlling hyperglycemia and hypertension and inhibiting the renin-angiotensin system." (PMID 26064987, 2015). "We hypothesized that FT011 would attenuate retinopathy in diabetic Ren-2 rats, which exhibit hypertension due to an overactive extra-renal renin-angiotensin system." (PMID 26222724, 2015). "First, renin–angiotensin system (RAS) dysregulation in NAFLD might lead to the development of hypertension, as RAS dysregulation may play a key role in hepatic inflammation and fibrosis." (PMID 26618774, 2015). "The Na+/H+ exchanger 3 in the proximal tubule is also key in maintaining basal blood pressure and the development of angiotensin II hypertension, a phenomena that should be of interest in blacks that predominantly have salt sensitive and low renin hypertension compared to the white population." (PMID 26486596, 2015). "RenTgMK mice develop hypertension because of high renin activity." (PMID 26494430, 2015). "PATHWAY 2 is the first robust RCT to evaluate the optimal treatment/s for resistant hypertension and will define whether treatment can be best stratified according to plasma renin levels." (PMID 26253568, 2015). "It has been postulated that estrogen may be protective against end organ damage from hypertension, although Reckelhoo12 emphasized the role of the renin-angiotensin system (RAS) in blood pressure regulation." (PMID 25834670, 2015). "It has not yet been fully elucidated whether cardiac tissue levels of prorenin, renin and (P)RR are activated in hypertension with a high salt intake." (PMID 25799069, 2015). "Renin in the cardiovascular system is primarily kidney-derived as a response to systemic blood pressure and blood volume and its expression can dynamically change during developing hypertension." (PMID 25766467, 2015). "Among the genetic markers commonly involved, the polymorphisms of several genes, including those encoding vasoactive metabolites such as the components of the renin-angiotensin system (RAS), have been proposed as candidates in association with essential hypertension." (PMID 26351579, 2015). "Thus whilst ET antagonists in left ventricular heart failure produce the desired vasodilatation, this is offset by fluid retention and activation of the renin hypertension system." (PMID 24582810, 2014). "In our case, both renin and aldosterone blood levels were significantly elevated, with a normal renin/aldosterone ratio confirming the appropriate activation of RAAS, suggestive of renal cause of hypertension." (PMID 25177679, 2014). "Moreover, spontaneous development (SHR), transgenic (dTGR: double transgenic rats harbouring human renin and angiotensin genes) and mechanical induction (e.g., aortic constriction) of hypertension are widely used for this purpose." (PMID 24877123, 2014). "CKD-related complications such as proteinuria or hypertension could then be treated with a renin-angiotensin-aldosterone antagonist such as an ACE-inhibitor or an angiotensin receptor blocker." (PMID 25416588, 2014).
Hypertension (continued). "The renin-angiotensin system is important in the regulation of blood pressure and hydromineral balance, and its activation is one of the key factors in the etiology of Mets, particularly hypertension." (PMID 24959250, 2014). "The cardiovascular effects of vitamin D may be mediated through the PTH axis and linked to reduced concentrations of serum ionized calcium, especially in low-renin human hypertension prevalent among African Americans." (PMID 25505940, 2014). "Therefore, the absence of vitamin D receptor activation leads to tonic upregulation of the renin-angiotensin system, eventually leading to hypertension and left ventricular hypertrophy." (PMID 24586986, 2014). "Genes associated with renin-angiotensin-aldosterone system, such as angiotensinogen (AGT), angiotensin converting enzyme (ACE) and angiotensin II receptor 1 (AGTR1), were the most extensively studied as hypertension candidate genes." (PMID 25313554, 2014). "In addition to its role in hypertension, the renin-angiotensin-aldosterone system also plays an important role in mediating vascular remodeling in neointimal hyperplasia after angioplasty and atherosclerosis." (PMID 24804145, 2014). "These pathophysiologic changes are not specific for reninoma and are usually present in all renin-mediated causes of hypertension." (PMID 25177679, 2014). "Due to this, renin is regarded as one of the most effective targets to treat hypertension." (PMID 24445304, 2014). "The renin-angiotensin-aldosterone system (RAAS) is a major mediator of hypertension." (PMID 25280587, 2014). "Thus, we demonstrated the role of hydrolysates of fried egg and individual fractions in controlling hypertension through multiple mechanisms of action, involving modulation at the levels of the renin-angiotensin system, nitric oxide, and oxidative stress." (PMID 25502445, 2014). "We found that db sham mice did not develop spontaneous hypertension, while db RAS mice develop hypertension to an extent that is similar to that observed in WT RAS mice, yet associated with transient but more prolonged increases in plasma renin activity and greater renal Ren1 expression." (PMID 24708836, 2014). "We therefore hypothesized that aldosterone secretion from the zona glomerulosa in patients with IHA and low-renin essential hypertension is regulated not only by ACTH but also by clock genes." (PMID 25239966, 2014). "As the initiation factor of renin-angiotensin system, renin plays a critical role in hypertension." (PMID 23825541, 2013). "Renin-angiotensin-aldosterone system (RAAS) is the most important endocrine blood pressure control mechanism in our body, genes encoding components of this system have been strong candidates for the investigation of the genetic basis of hypertension." (PMID 24015270, 2013). "Therefore, in the present work, we used azilsartan as an ARB to elucidate the potential role of the renin‐angiotensin system in the mechanism of hypertension in SHRcp." (PMID 23629805, 2013). "Genetic deletion of TWIK-related acid sensitive K+ channels (known as TASK1) not only leads to low-renin hypertension, attributed to the autonomous overproduction of aldosterone, but also a marked depolarization of the adrenal zona glomerulosa cell membrane potential." (PMID 23382865, 2013). "Uric acid can induce pre-glomerular arterial disease, vascular proliferation, renal inflammation, and hypertension via an activation of renin-angiotensin system and cyclooxygenase-2, which in turn aggravates renal disease, endothelial dysfunction, hypertension, and cardiovascular disease." (PMID 24308550, 2013). "According to the AB/CD algorithm, both treatment arms of NOAAH included a drug class that addressed the low-renin volume component of hypertension (hydrochlorothiazide and amlodipine) as well as an agent (bisoprolol and valsartan) interfering with the high-renin vasoconstrictor component." (PMID 23803591, 2013).
Hypertension (continued). "Thus, the coplacement technology is a promising tool for the generation of a relevant animal model to decipher the role of PPARgamma and Pal3 in the stimulation of the renin production and the development of arterial hypertension during MetS." (PMID 24288524, 2013). "However, excessive aldosterone secretion can result in hypertension, low plasma renin, and hypokalemia." (PMID 23382865, 2013). "A major discovery was evidence for REN mRNA regulation via binding of miRNAs hsa-miR-181a and hsa-miR-663 to its 3′ UTR as the observed downregulation of these 2 miRNAs in hypertension could explain the elevation in intrarenal renin mRNA." (PMID 24575418, 2013). "In addition, endothelial dysfunction is a relevant phenomenon in obesity and obesity-induced hypertension: stimulation of the renin-angiotensin system, in obese individuals, activates Nox, xanthine oxidase and NOS." (PMID 23698776, 2013). "Hypertension and CKD cluster in obese and/or diabetic subjects, and both disease states share common underlying pathways, such as chronic low-grade inflammation, increased sodium retention, and an activated renin-angiotensin system." (PMID 23509612, 2013). "Furthermore, the importance of the renin-angiotensin system to vascular inward remodeling has been confirmed in human essential hypertension." (PMID 23805104, 2013). "The HC is one of the human proteases that has attracted considerable interest from several of the major pharmaceutical companies as a potential medical target for anti-inflammatory treatments and also for the treatment of high blood pressure outside the renin-angiotensin system." (PMID 23840386, 2013). "Vitamin D could also be involved in the pathogenesis of arterial hypertension via stimulation of the renin–angiotensin system." (PMID 23781303, 2012). "Third, according to the ABCD algorithm both treatment arms of NOAAH include a drug class that addresses the low-renin volume component of hypertension (hydrochlorothiazide and amlodipine) as well as agents (bisoprolol and valsartan) interfering with the high-renin vasoconstrictor component." (PMID 22594907, 2012). "Over the past decades, our laboratory has shown that these pathological conditions are present as a result of the hypertension induced by the activation of the renin-angiotensin system (RAS) in the rat, which are also observed in the RAS-dependent hypertensive mouse." (PMID 23193440, 2012). "The additive effect of angiotensin II may favor electroneutral sodium reabsorption during hypovolemia and may contribute to hypertension in diseases with an activated renin–angiotensin–aldosterone system." (PMID 22549242, 2012). "Interestingly, REN and ADIPOQ also present polymorphisms, which seem linked to therapeutic response to hypertension." (PMID 23282288, 2012). "Furthermore, because the transgene is of mouse origin, the resulting high circulating active renin can interacts with other components of the mouse RAS leading to a severe Ang II-mediated hypertension and to kidney damage." (PMID 23300650, 2012). "Blood pressure in CKD patients is increased due to fluid overload and production of vasoactive hormones via renin-angiotensin system which might aggravate hypertension." (PMID 22935602, 2012). "Regarding hypertension, renin (REN) is part of the renin-angiotensin system (RAS)." (PMID 23282288, 2012). "In obese individuals, the impaired vitamin D endocrine system could act on renin-angiotensin system and also in vascular function and induce hypertension." (PMID 22363895, 2012). "Furthermore, 2K1C model induces renin-angiotensin-aldosterone dependent hypertension and another explanation for reduced NO bioavailability in this model of hypertension is that, high angiotensin II level decreases NO level by promoting oxidative stress." (PMID 23493527, 2011).